MTOR (mechanistic target of rapamycin kinase)
Diseases named in the same sentence as MTOR in open-access papers (continued):
Sharing a sentence is not in itself a finding about the gene and the disease.
tumor (continued). "Consistently, PTC cells with altered circ_0092278 expression led to corresponding changes in the levels of phosphorylated PI3K/AKT/mTOR in tumor tissues following in vivo tumor formation." (PMID 40537911, 2025). "Both ICGA-A and CRA therapies were also found to suppress tumor proliferation by inhibiting the FAK/PI3K/AKT/mTOR signaling pathway." (PMID 40109332, 2025). "Immunohistochemical analysis of tumor tissues revealed that in addition to p-mTOR and p-p65, the tumor proliferation index Ki67 was also increased in the LPS groups." (PMID 40817754, 2025). "These mutations typically result in a loss of TMEM127 function, leading to aberrant activation of the mTOR signaling pathway and promoting tumor development." (PMID 41357074, 2025). "These include the induction of apoptosis, inhibition of tumor proliferation, and modulation of key oncogenic signaling pathways, such as nuclear factor-kappa B (NF-κB) and the protein kinase B/mammalian target of rapamycin (Akt/mTOR) axis." (PMID 40574063, 2025). "Treatment of SEGA is surgical, with the removal of the tumour, or medical, with the use of mammalian target of rapamycin (mTOR) inhibitors." (PMID 40035895, 2025). "We refer the interested reader to our review of PI3K/AKT/mTOR inhibition in canine neoplasms for more information about these studies." (PMID 41106249, 2025). "For instance, the PI3K/AKT/mTOR signaling pathway is closely related to apoptosis, and inhibiting this pathway can enhance the sensitivity of tumor cells to apoptosis." (PMID 40331942, 2025). "The PI3K/AKT/mTOR pathway, as a primary regulator of cell growth and survival, has been shown to promote tumor cell proliferation, inhibit apoptosis, and enhance drug resistance when aberrantly activated factors that are crucial in HCC progression." (PMID 39972480, 2025). "Recent study has revealed that lactate generated by the glycolysis of tumor cells within TME stimulates the mTOR pathway, resulting in the phosphorylation of the transcription factor TFEB and impeding its nuclear translocation." (PMID 40755753, 2025). "The interaction between integrin α2/β1 and S. moorei cellwall protein Cna B-type domain-containing protein activated the PI3K-Akt-mTOR pathway, resulting in C-myc activation and promoting tumor growth and progression." (PMID 39990665, 2025). "Hyaluronan carried by tumor-derived microvesicles induces IL-10 production in classical (CD14++CD16−) monocytes via PI3K/Akt/mTOR-dependent signaling pathway." (PMID 40328660, 2025). "Among them, suppression of mammalian target of rapamycin (mTOR) signaling pathway by the LKB1-AMPK pathway is considered to be an important tumor-suppressive function." (PMID 40544190, 2025). "The PI3K/Akt/mTOR signalling pathway is an important pathway that regulates the cell cycle and is directly related to tumour growth, proliferation, and apoptosis." (PMID 40149700, 2025). "The AKT/mTOR signaling pathway is related to the regulation of various biological behaviors in tumor cells and plays a key role in the occurrence and development of BRCA." (PMID 39910045, 2025). "Tumor cells often develop resistance to inhibitors of the PI3K/AKT/mTOR pathway through compensatory activation of alternative pathways, such as MAPK/ERK and Wnt/β-catenin." (PMID 40072110, 2025). "This switch is accompanied by changes in the PI3K/AKT pathway and the inhibition of mTOR, which collectively contribute to the minimization of microvascular density and suppression of tumor growth." (PMID 40282330, 2025). "PTEN, a well-known tumor suppressor gene, regulates the PI3K/AKT/mTOR signaling pathway, which is crucial for tumor progression, metastasis, and angiogenesis in both KIRC and KIRP." (PMID 40649942, 2025). "Upregulation of mTOR was found to overcome these effects, thereby highlighting the essential role of this axis in autophagy‐mediated tumor suppression." (PMID 40740483, 2025).
tumor (continued). "Modulating SASP composition through NF-κB inhibition has been shown to reduce tumor-promoting secretions, with metformin and mTOR inhibitors (e.g., rapamycin) effectively suppressing NF-κB-driven SASP." (PMID 40703657, 2025). "In view of this, jointly targeting the POSTN-integrin and the AKT/mTOR signaling pathway can synergically disrupt the tumor-promoting signaling network." (PMID 41018265, 2025). "AKT and GSK3β are core regulatory molecules of the PI3K/AKT/mTOR signaling pathway, playing important roles in tumor development and progression." (PMID 40860827, 2025). "Preclinical and clinical research have identified a viable candidate in mTOR suppressor drugs, such as temsirolimus, which have demonstrated efficacy in anti-tumor preclinical models." (PMID 40881676, 2025). "The incorporation of mTOR inhibitors to curb tumor progression in kidney transplant recipients (KTRs) appears promising with respect to overall survival, although definitive outcomes for complex RCC remain undetermined." (PMID 41301732, 2025). "Since mTOR is a major inducer of cell growth and proliferation, loss of VHL function can lead to increased mTOR signaling and tumor growth." (PMID 39920694, 2025). "By triggering the Akt/mTOR pathway, PD-L1-mediated reverse signaling can improve the glycolytic metabolism of PD-L1-positive tumor cells, hence speeding up tumor growth, according to mechanistic research." (PMID 41451233, 2025). "P03 also has mutations in MTOR and ELF3, while P04 has mutations in FGFR1, and P05 has mutations in PIK3CA and NTRK1–genes involved in tumor growth and survival." (PMID 41012124, 2025). "The PI3K/AKT/mTOR pathway emerges as a central driver of tumor progression, metastasis, and therapeutic resistance." (PMID 40979744, 2025). "As mTOR regulates critical processes like protein synthesis and angiogenesis—both vital for tumour growth—its inhibition by QRT effectively hampers tumour progression." (PMID 40084006, 2025). "Nab-sirolimus (combination of sirolimus and everolimus), is a nanoparticle albumin-bound MTOR inhibitor which has shown promising preclinical data with increased MTOR suppression and decreased tumor growth." (PMID 40564038, 2025). "Consistent with the in vitro results, treatment with F. rodentium and its metabolites significantly suppressed CLEC-2 protein expression and the PI3K/AKT/mTOR signaling pathway in tumor tissues." (PMID 40693815, 2025). "Alterations in PTEN, a negative regulator of the PI3K/AKT/mTOR signaling pathway, further contribute to tumor growth and resistance to apoptosis." (PMID 41463261, 2025). "The mTOR complex integrates signals from growth factors and nutrients, thereby facilitating cellular responses that promote tumor survival and growth." (PMID 40429864, 2025). "In breast cancer brain metastases, PI3K/Akt/mTOR pathway promotes tumor growth and therapeutic resistance." (PMID 39857798, 2025). "The phosphoinositide-3 kinase (PI3K)/Akt/mammalian target of rapamycin (mTOR) signaling axis (PI3K/Akt/mTOR) is an important regulator of tumor cells’ proliferation, growth, metabolism, and survival." (PMID 41283264, 2025). "The key pathways, such as MAPK/ERK, PI3K/AKT/mTOR, and Wnt/β-catenin, are presented in the context of tumor progression." (PMID 40227591, 2025). "AIM2 was demonstrated to impede the proliferation and migration of CRC cells through the suppression of the AKT/mTOR signaling pathway and the inhibition of Glil expression, thereby exerting a tumor suppressor effect." (PMID 39744568, 2025). "The advantageous effect of mTOR inhibitors is the shrinking of SEGA when tumours are large and infiltrate surrounding brain tissue." (PMID 40035895, 2025). "The role of mTOR inhibitors worked through the promotion of glycolysis in M2-type TAMs, thereby suppressing their tumor-promoting effects." (PMID 40611261, 2025).
tumor (continued). "Given the role of mTOR signaling in the regulation of tumor cell metabolism and radioresistance, mTOR inhibitors have been explored as potential radiosensitizers for combination therapy." (PMID 40963930, 2025). "PAK1 is involved in the PI3K/AKT/mTOR pathway, contributing to tumor growth by activating β-catenin." (PMID 40699726, 2025). "Literature indicates that BA suppresses PD-L1 expression and modulates the AKT/mTOR signaling pathway, potentially mitigating tumor immune tolerance in vivo and offering a novel approach for anti-tumor immunotherapy." (PMID 40356970, 2025). "FGF21 suppresses the PI3K/AKT/mTOR/70S6K pathway, demonstrating that downregulation of this axis stimulates autophagy to restrict tumor growth and enhance apoptosis." (PMID 40740483, 2025). "Temsirolimus is an mTOR inhibitor that can inhibit tumour growth by regulating the mTOR signalling pathway." (PMID 40591061, 2025). "mTOR is involved in multiple signaling pathways, including the PI3K/AKT/mTOR pathway, which plays an essential role in tumor formation and development, and the LKB1‐AMPK‐TSC‐mTOR pathway, which regulates energy metabolism." (PMID 40439275, 2025). "Two strategies for targeting the mTOR signaling pathway:Inhibiting the tumor mTOR signaling pathway to reduce resource depletion in the TME;Enhancing NK cell metabolism directly by activating the PI3K–Akt–mTOR signaling pathway via BPQDs@HSA." (PMID 40959206, 2025). "We even validated mTOR protein levels and demonstrated that it was detectable exclusively in the 3D system including both cell lines, as well as in the actual tumor tissue, compared to single cell line culture, or 2D co-culture." (PMID 41220928, 2025). "Among several ways to enhance the efficacy of ICI, trials are exploring combining ICIs with serine/threonine‐protein kinase mTOR (mTOR) inhibitors in different tumor types." (PMID 39258533, 2025). "In studies focused on cell proliferation inhibition, hyperoside was shown to inhibit the activity of the Akt/mTOR/p70S6K signaling pathway in a dose-dependent manner, promoting autophagy and thereby exerting anti-tumor effects." (PMID 40098612, 2025). "In PCa, PI3Kδ is integral to other PI3K subunits and is involved in the activation of the AKT/mTOR signaling pathway, which is crucial for tumor cell proliferation, survival, and metabolism." (PMID 40427108, 2025). "Experiments in vivo demonstrated that ART significantly delayed the growth of subcutaneous tumors in nude mice, further highlighting its potent anti-tumor effects through inhibition of the PI3K/AKT/mTOR signaling pathway." (PMID 40303931, 2025). "In these tumors, enhanced mTOR signaling contributes to both tumor growth and neuronal hyperexcitability." (PMID 41074169, 2025). "We will examine the molecular underpinnings of mTOR signaling in tumor cells and peritumoral neurons, emphasizing how these insights can inform the development of novel therapeutic strategies." (PMID 41301687, 2025). "Targeting the PI3K/AKT/mTOR pathway in PDEECs offers a promising therapeutic strategy, given the frequent alterations observed within this pathway in these aggressive tumor subtypes." (PMID 40072110, 2025). "Apart from this, chronic p62 accumulation drives the sustained activation of NF-κB, NRF2, and the mTOR pathway, which collectively promote tumor survival and progression." (PMID 40789840, 2025). "IF has been shown to modulate this signaling pathway by decreasing circulating IGF-1 levels, leading to downregulation of the PI3K/AKT/mTOR pathway, a central driver of tumor growth." (PMID 41008741, 2025). "Everolimus (EVR), an oral mTOR inhibitor, has been widely adopted in oncology with established indications across multiple tumor types." (PMID 40979744, 2025). "Previously, the PI3K/AKT/mTOR pathway has been shown to be downregulated in R132H-driven tumors and tumor models." (PMID 40188944, 2025).
tumor (continued). "Inhibits GNMT, abolishing its tumor suppressor function by ceasing to inhibit the mTOR pathway, leading to cell proliferation." (PMID 41465470, 2025). "The PI3K/Akt/mTOR signaling pathway is one of the most commonly dysregulated pathways in tumors, playing a crucial role in promoting tumor initiation, progression, and treatment." (PMID 40704062, 2025). "Dysregulation of key signaling pathways such as NF-κB, MAPK, PI3K/Akt/mTOR, and Kynurenine/AhR highlights how microbiota-driven mechanisms promote tumor growth and facilitate immune evasion." (PMID 40075568, 2025). "The mammalian target of rapamycin (mTOR) is a phosphorylase that can stimulate tumor growth by acting on proteins that control cell division and proliferation." (PMID 40149343, 2025). "Research investigated ACTR3 expression levels related to PI3K/Akt/mTOR pathway and its influence on tumor immunology and clinical outcomes." (PMID 41366959, 2025). "When TSC2 function is impaired, mTOR/4EBP1/c‐Myc signaling becomes abnormally activated, enhancing tumor stemness." (PMID 40433832, 2025). "Beyond its role in tumor cells, the mTOR signaling pathway balances the differentiation and functional state of immune cells within the tumor microenvironment." (PMID 41429766, 2025). "These factors collectively promote tumor growth through activation of the PI3K/Akt/mTOR signaling pathway." (PMID 40678319, 2025). "Activation of the PI3K/Akt/mammalian target of rapamycin (mTOR) signaling axis also facilitates angiogenesis—promoting the formation of new blood vessels—which enhances tumor vascularization and supports tumor progression." (PMID 41133538, 2025). "EGFR (Epidermal Growth Factor Receptor) overexpression, driven by hypomethylation, activates oncogenic pathways such as RAS/RAF/MEK/ERK and PI3-K/Akt/mTOR, which promote tumor proliferation, survival, angiogenesis, and resistance to therapy." (PMID 40881676, 2025). "PTEN is a known negative regulator of the PI3K/AKT/ mTOR signaling cascade, a key pathway promoting tumor cell growth." (PMID 41426972, 2025). "Tumor glucose consumption metabolically restricts T cells, leading to diminished mammalian target of rapamycin (mTOR) activity, reduced glycolytic capacity, and decreased IFN-γ production." (PMID 40070825, 2025). "PTEN is a tumor suppressor gene that regulates the PI3K/AKT/mTOR signaling pathway, which is involved in cell proliferation and survival." (PMID 39744583, 2025). "To unravel the underlying mechanism behind mTOR pathway overexpression in FAP1 organoids, we examined PTEN, a crucial tumor suppressor gene that negatively regulates mTORC1." (PMID 40702333, 2025). "The abnormal activity of the PI3K/AKT/mTOR pathway often induces cellular overgrowth and apoptosis resistance and tumor progression." (PMID 40142329, 2025). "In the BxPC-3 xenograft model, bardoxolone methyl treatment led to a significant reduction in tumor volume, accompanied by diminished expression of p-Akt and p-mTOR within the tumor microenvironment." (PMID 40732256, 2025). "Bone metastatic tumor tissues exhibited significantly elevated mTOR expression levels compared to other sites." (PMID 41050665, 2025). "PTEN (Phosphatase and Tensin Homolog) is a tumor suppressor that negatively regulates the PI3K/Akt/mTOR pathway by dephosphorylating PIP3 back to PIP2, thus inhibiting Akt activation." (PMID 40080721, 2025). "The PI3K/AKT/mTOR pathway is instrumental in EMT in malignant tumours, aiding in the transition to a more aggressive phenotype, which is essential in aspects such as cell survival, growth, proliferation, angiogenesis, transcription, translation and metabolism." (PMID 40665565, 2025).
tumor (continued). "MTF is a rapamycin agent that inhibits mTOR that has demonstrated the ability to enhance the sensitivity of tumor cells to chemotherapy drugs." (PMID 40385549, 2025). "When combined with abemaciclib (a CDK4/6 inhibitor), alpelisib (a PI3K inhibitor), or everolimus (a mTOR inhibitor), imlunestrant demonstrates enhanced anti-tumor efficacy, including against brain metastases, irrespective of ESR1-mutation status." (PMID 40641933, 2025). "The interaction between ER signaling and other molecular pathways, such as PI3K/AKT/mTOR, influences tumor growth and endocrine resistance." (PMID 40299687, 2025). "Activation of Ras/Raf/MEK/ERK and PI3K/AKT/mTOR pathways by EGF promotes tumor growth, while SRC facilitates invasion and metastasis by enhancing cytoskeletal reorganization." (PMID 40226632, 2025). "In the NSCLC cell line A549, hyperoside promotes autophagy by effectively inhibiting the PI3K/Akt/mTOR signaling pathway, thereby exerting its anti-tumor effects." (PMID 40098612, 2025). "Our tumor cell panel included key clinical markers (ER, HER2, and Ki67), markers of growth-associated signaling pathways (p-mTOR, pRb, and pS6), markers relevant for immune interactions (HLA-ABC and PD-L1), and key lineage markers (CK5, CK14, and GATA3)." (PMID 39437149, 2025). "YAP-mediated tumor initiating cell programs included activation of oncogenic transcriptional networks and mTOR signaling, and recruitment of myeloid cells to the invasive front contributing to tumor infiltration." (PMID 39779672, 2025). "This interaction inhibits the mTOR signaling pathway, leading to the suppression of tumor cell proliferation, transformation, and angiogenesis." (PMID 40909959, 2025). "Loss of PTEN is common in cancers, resulting in unrestrained activation of the AKT/mTOR pathway, promoting tumor growth and survival." (PMID 40014097, 2025). "Activation of DRD5 by the selective agonist SKF83959 upregulates reactive oxygen species (ROS) levels in tumor cells, thereby activating the mitochondrial apoptosis pathway while inhibiting the mTOR pathway to induce autophagic cell death." (PMID 40873563, 2025). "The PI3K/AKT/mTOR signaling axis was selected for investigation due to its well-established role in promoting tumor growth, survival, and therapy resistance in TNBC." (PMID 41141380, 2025). "Preclinical studies suggest that mTOR inhibitors (e.g., rapamycin, RAD001), combined with standard therapies, reduce tumor burden and prolong survival in HPV-associated cancers." (PMID 40667502, 2025). "Among 43 TCGA-HNSC subjects with RNAseq data for paired tumor and normal tissue, we observed that both YAP and mTOR signaling were enriched in tumor compared to normal tissue." (PMID 39779672, 2025). "Previous studies have also shown that MAGEA3 can regulate the ubiquitination degradation of AMPK, as well as activate the mTOR pathway and inhibit the autophagy pathway, which can also impact the metabolic status of tumor cells." (PMID 40342736, 2025). "It has been shown 26 that low or intermittent administration of mTOR inhibitors has an anti-tumor effect, while excessive doses of mTOR inhibitors exert a strong immunosuppressive effect." (PMID 40969386, 2025). "mTOR plays critical roles in cell metabolism, growth, proliferation, and survival, and mTOR inhibition impairs tumor cell proliferation by repressing metabolic pathways critical for protein and lipid biosynthesis." (PMID 40940986, 2025). "Sirolimus, an oral mTOR inhibitor, has emerged over the past decade as a highly effective alternative, demonstrating rapid hematologic recovery, tumor regression, and an acceptable safety profile in both prospective studies and real-world series." (PMID 41300547, 2025).